SLIT3 (slit guidance ligand 3)
Diseases named in the same sentence as SLIT3 in open-access papers (continued):
Sharing a sentence is not in itself a finding about the gene and the disease.
SLIT3 also shares sentences with these, for which no sentence is quoted: depression (3 papers); gastric cancer (3); hepatocellular carcinoma (3); rheumatoid arthritis (3); acute myeloid leukemia (1); adenocarcinoma (1); aortic stenosis (1); atrial septal defect (1); colon adenocarcinoma (1); colorectal tumours (1); congenital diaphragmatic hernia (1); Crohn disease (1); diseases of the central nervous system (1); endometriosis (1); epilepsy (1); esophageal cancer (1); heart defects (1); Hernia (1); Hypertension (1); infection (1); Intellectual disability (1); interstitial lung disease (1); intracerebral hemorrhage (1); intraepithelial neoplasia (1); male infertility (1); metastatic tumor (1); Mitral regurgitation (1); nasopharyngeal carcinoma (1); neurological diseases (1); non-small cell lung carcinoma (1).
A further 7 diseases each share a sentence with SLIT3 in 1 paper.